SNX8 (sorting nexin 8)
Description:
May be involved in several stages of intracellular trafficking. May play a role in intracellular protein transport from early endosomes to the trans-Golgi network.
Synonyms: Mvp1
Tractability: Antibody: UniProt places it where antibodies can reach, with high confidence. PROTAC: ubiquitination databases record sites on it; its protein half-life has been measured.
Gene: Protein-coding gene on chromosome 7 (2,251,770 to 2,354,318, reverse strand). Ensembl gene ENSG00000106266.
Subcellular location: Early endosome membrane
Subcellular location (Human Protein Atlas): Vesicles
Gene Ontology:
Molecular function: identical protein binding; phosphatidylinositol binding; protein binding
Biological process: early endosome to Golgi transport; intracellular protein transport; retrograde transport, endosome to Golgi
Cellular component: early endosome membrane; retromer complex; cytoplasmic vesicle; cytosol
Genetic constraint (gnomAD): Loss-of-function variants: 20 observed, 39.17 expected, observed/expected ratio (o/e) 0.51, 90% interval 0.36 to 0.74. The upper end of that interval is the gene's LOEUF score, 0.74, which puts it in group 3 of 6, group 1 being the genes least tolerant of losing a copy. Missense variants: 632 observed, 537.84 expected, observed/expected ratio (o/e) 1.18, 90% interval 1.1 to 1.25. Synonymous variants: 298 observed, 246.47 expected, observed/expected ratio (o/e) 1.21, 90% interval 1.1 to 1.33.
Homologues: Orthologues: chimpanzee SNX8 (99% identical), macaque SNX8 (98% identical), pig SNX8 (87% identical), rat Snx8 (87% identical), guinea pig SNX8 (85% identical), dog SNX8 (85% identical), mouse Snx8 (81% identical), tropical clawed frog SNX8 (70% identical), zebrafish snx8a (58% identical), zebrafish snx8b (46% identical). Paralogues in human: SNX18 (20% identical), SNX33 (18% identical), SNX2 (16% identical), SNX9 (16% identical), SNX1 (15% identical), SNX4 (15% identical), SNX5 (15% identical), SNX6 (15% identical), SNX30 (14% identical), SNX7 (14% identical), SNX32 (14% identical), SNX11 (10% identical), and 3 more.
Diseases named in the same sentence as SNX8 in open-access papers:
SNX8 is named in the same sentence as 17 diseases in open-access papers, as found by Europe PMC text mining. Sharing a sentence is not in itself a finding about the gene and the disease. The quoted sentences say what the papers report.
Alzheimer disease (5 papers, 2014 to 2024). A progressive, neurodegenerative disease characterized by loss of function and death of nerve cells in several areas of the brain leading to loss of cognitive function such as memory and language. "SNX8’s role in endosomal content sorting has been implicated in the risk for neuropathologies, i.e., for late onset Alzheimer’s disease." (PMID 29884837, 2018). "Similarly, SNX8, the human homolog of Mvp1, which has been also implicated in Alzheimer’s disease, mediates formation of an endosomal recycling tubule." (PMID 34524084, 2021). "Changes in the expression of other genes associated with increased risk of developing Alzheimer's disease were also observed including sorting nexin 8 (SNX8) and apolipoprotein D (Apod), which is up-regulated in pathological and stress condition including Alzheimer's disease." (PMID 25202975, 2014).
Cognitive impairment (2 papers, 2019 to 2021). Abnormal cognition is characterized by deficits in thinking, reasoning, or remembering. "Interestingly, overexpression of SNX8 reduces Aβ levels and rescues cognitive impairment in an APP/PS1 AD mouse model." (PMID 34524084, 2021). "Given that prolonged SNX8 overexpression can ameliorate cognitive impairment at late stages in APP/PS1 mice, it seems likely that restoration of SNX8 function at early stages of AD onset may confer protective effects during advanced stages of disease onset." (PMID 31551717, 2019). "Importantly, SNX8 overexpression rescued cognitive impairment in APP/PS1 mice." (PMID 31551717, 2019). "Our results here indicate that SNX8 levels are attenuated in human AD and mouse APP/PS1 AD models; SNX8 mediates APP trafficking from amyloidogenic endosomal compartments, and suppresses Aβ generation and cognitive impairment in APP/PS1 mice." (PMID 31551717, 2019). "So far, our results indicate that reductions in SNX8 levels in human AD and mouse APP/PS1 AD models may potentially enhance amyloidogenic APP processing to promote Aβ accumulation and cognitive impairment." (PMID 31551717, 2019). "This suggests that SNX8 overexpression may attenuate amyloidogenic APP processing and cognitive deficits." (PMID 31551717, 2019). "Interestingly, AAV-mediated SNX8 overexpression in APP/PS1 mouse brain reduced Aβ levels and reversed cognitive impairments in Y-maze tests." (PMID 31551717, 2019). "Together, these results implicate a neuroprotective role for SNX8 in enhancing non-amyloidogenic APP trafficking, thereby suppressing Aβ accumulation and consequent cognitive impairment in AD." (PMID 31551717, 2019).
viral infection (2 papers, 2018 to 2021). "To investigate the roles of SNX8 in host defense against viral infection in vivo, we infected Snx8+/+ and Snx8-/- mice with HSV-1 by intraperitoneal (i.p.)injection and monitored their survival." (PMID 30321235, 2018).
COVID-19 (1 paper, 2024). A disease caused by infection with severe acute respiratory syndrome coronavirus 2. "This suggests that autoreactivity to ERFL, SNX8 and KDELR1 is a significant feature of MIS-C that is separable from SARS-CoV-2 exposure and severe acute paediatric COVID-19." (PMID 39112696, 2024).
Hepatic steatosis (1 paper, 2023). Steatosis is a term used to denote lipid accumulation within hepatocytes. "It was shown that the steatosis and lipogenic pathways were significantly exacerbated in the livers of Snx8 knockout mice, whereas overexpression suppressed high-fat, high-cholesterol (HFHC)-diet-induced hepatic steatosis." (PMID 37764494, 2023).
Listeria infection (1 paper, 2018). "Our previous study has demonstrated that SNX8 mediates IFNγ-triggered non-canonical signaling pathway and host defense against Listeria infection." (PMID 30321235, 2018).
measles (1 paper, 2023). A highly contagious viral infection caused by the measles virus. "In measles, including six in whole blood (SOAT1, COLGALT2, AC021860.1, HCG11, METTL21B, and MRPL10), six in the lung tissue (GSTM4, PAQR6, RP11-617D20.1, SNX8, METTL21B, and ANKRD27), and two in the transformed fibroblast cells (CBWD2, and TSFM)." (PMID 37020999, 2023).
infection (2 papers, 2018 to 2024). The state of being infected such as from the introduction of a foreign agent such as serum, vaccine, antigenic substance or organism. "Furthermore, confocal microscopy revealed that SNX8-deficiency markedly inhibited the trafficking of MITA from the ER via Golgi to perinuclear microsomes induced by infection of HSV-1." (PMID 30321235, 2018).
cancer (1 paper, 2019). A tumor composed of atypical neoplastic, often pleomorphic cells that invade other tissues. "Although more than 90% of GC/SC tissues expressed the SNX8 protein, as per the immunohistochemistry results based on data in the Human Protein Atlas (unpublished data), no study has assessed the role of SNX8 expression in any cancer." (PMID 31652813, 2019).
SNX8 also shares sentences with these, for which no sentence is quoted: heart malformations (1 paper); Intellectual disability (1); Neurodevelopmental delay (1); neurodevelopmental disorder (1); Parkinson disease (1); schizophrenia (1); steatosis (1); tumor (1).